IFNG (interferon gamma)
Diseases named in the same sentence as IFNG in open-access papers (continued):
Sharing a sentence is not in itself a finding about the gene and the disease.
infection (continued). "To further indicate the role of NKT-monocyte signaling through IFNγ in infection control, we used anti-IFNγ neutralizing antibodies to block IFNγ, and measured its effect on intracellular bacterial survival within PBMCs." (PMID 31332193, 2019). "While Th17 cells induce factors (e.g., IL-17, IL-8) involved in neutrophil recruitment at the site of infection, they are also shown to be responsible for recruiting IFNγ-producing protective memory CD4+ Th1 cells to the site of Mtb infection." (PMID 30873180, 2019). "While IFNγ secreting cells were spotted already five days following infection, serum antibodies were detected only 10 days post infection." (PMID 31443439, 2019). "The use of IL10-targeting siRNA revealed that IL10 inhibited the production of IL1B, IL6, tumour necrosis factor (TNF) and interferon gamma (IFNG) during infection of bMDM with the M. bovis strain G18." (PMID 31527895, 2019). "We further investigated soluble proinflammatory cytokines in plasma and lung homogenates (IL-1β, KC/GRO, TNFα, IL-6, IL-12p70, and IFNγ) as well as pulmonary influx of myeloid-derived cells 2 weeks into COXi treatment (week 6 of infection)." (PMID 31396568, 2019). "We investigated the impact of IFNγ‐priming on host cell death in PMA‐differentiated human THP‐1 macrophage‐like cells upon infection with type I (RH) and type II (Pru) Tg, which differ in their virulence effector repertoire." (PMID 31268602, 2019). "Stimulation with IFNγ resulted, after 2 h of infection, in an eight-times increase in de novo transcribed Nampt RNA levels, followed by a rapid drop in Nampt mRNA." (PMID 30886604, 2019). "IL-1β–induced pro-inflammatory responses activate host defense during infection while IL-18 drives interferon-gamma (IFNγ) expression in T cells and NK cells." (PMID 30958862, 2019). "Exposure to 1 CFU resulted in infection of 50–80% of macaques as defined by the induction of an antigen-specific IFNγ secretion response (IGRA conversion)." (PMID 31736945, 2019). "IFNγ-mediated activation of macrophage antimicrobial defenses during in vivo infection is critical for host resistance to M. tuberculosis infection, and ex vivo treatment of cultured macrophages with this cytokine induces BMMs to inhibit bacterial replication." (PMID 31204998, 2019). "Collectively, these data show that the CD4+CD8+ T cells are the main IFNγ producers upon challenge infection of immunized pigs." (PMID 31620134, 2019). "By contrast, C. burnetii luminescence values continued to increase over the 5-days of infection when the IFNγ-treated cells were supplemented with tryptophan, which indicates that the intracellular bacteria remained more metabolically active." (PMID 31461509, 2019). "The SICCT and interferon gamma levels were compared between calves co-infected with M. bovis and F. hepatica and singly infected calves a number of weeks post infection." (PMID 31887151, 2019). "Our study expands the understanding of how IFNγ influences host cells during infection by two important pathogens." (PMID 31268602, 2019). "This notion is further reinforced by mixed AT/RC experiments using LCMV cl13 infection under conditions of IFNγ blockade." (PMID 31697793, 2019). "IFNγ stimulation of myeloid cells, thus, plays a critical role in mediating host resistance to infections by numerous intracellular bacteria and parasites." (PMID 31585982, 2019). "IFNγ also suppresses inflammation at the site of infection through the downregulation of the Th2 immune response, characterized by IL4 and IL10." (PMID 30766521, 2019). "The degrees of reliance on subsets of CD4 helper T cells in overcoming infection differ between males and females, where the levels of Th1 and interferon gamma (IFN-γ) responses in females have been reported to be higher than those in males." (PMID 30918059, 2019).
infection (continued). "At 21 d post-infection, birds in the antibiotic and synbiotic supplementation group had by 0.61, and 0.65% decreased IFNγ mRNA compared to the control group, respectively." (PMID 31600299, 2019). "We used RT-PCR to confirm IL-21-induced expression of Gzma and Gzmb mRNAs in the lung at 7 hr after infection, and IL-21-induced granzyme B and IFNγ protein production was detected by ELISA in bronchoalveolar lavage fluid at 7 hr after infection." (PMID 30969166, 2019). "Following TCR stimulation, antigen-specific TRM CD8+ T cells that form following a primary infection rapidly express IFNγ and mediate local inflammation in the tissue microenvironment." (PMID 30875408, 2019). "Of note, we found that NKT cells are the only cells which produce IFNγ 4-h post-infection based on our scRNA-seq data." (PMID 31332193, 2019). "A decreased IFNγ/IL-4 ratio is reportedly associated with impaired IFN-γ production, which blockades infection defense." (PMID 31849964, 2019). "In contrast, C. rodentium infected mice exhibited enhanced frequencies of IFNγ- and IL-17-producing cells at day 10 post infection." (PMID 31275322, 2019). "The medical team decided to restart the IFNγ treatment for 4 days inducing again the resolved infection accompanied by a quick improvement in clinic and in chest CT scan." (PMID 31690258, 2019). "C. burnetii collected from untreated cells (primary infection) gave rise to a FFU value that was almost a log higher than that isolated from IFNγ-treated cells infected in parallel." (PMID 31461509, 2019). "IFNγ‐priming of macrophages, which is crucial in restricting pathogen growth and controlling infection, upregulates key antimicrobial molecules that mediate cell‐intrinsic control of pathogens and enhances pyroptotic cell death." (PMID 31268602, 2019). "Rebounders also exhibited a higher cell infection efficacies, despite an early predominance of antiviral cytokines (IFNγ, IFNα, TNFα) over immuno-modulatory cytokines (IL10, TGFβ)." (PMID 30696429, 2019). "Antibiotic and synbiotic supplementation had significant effects on cecal tonsil IFNγ mRNA content at 3 (P < 0.01), 7 (P < 0.01), 14 (P < 0.01) and 21 (P < 0.01) d post-infection." (PMID 31600299, 2019). "We also found that during STm infection, IFNγ enhanced macrophage pyroptosis in a GBP1‐dependent manner." (PMID 31268602, 2019). "With the early upregulation of CXCL10 transcript, NK cells recruited during infection produce IFNγ that contributes to Th1 differentiation." (PMID 31440475, 2019). "IFNγ from natural killer cells at the very early infection phase and from T cells at the late infection phase can activate macrophages and promote phagocytosis." (PMID 32038650, 2019). "The MTB-specific immune response induced following infection was measured in each of the three macaque populations using a PPD-specific IFNγ ELISPOT assay." (PMID 30833652, 2019). "Our investigations on the transcriptional response of bMDM found that the production of TNF and IFNG in response to infection with both M. bovis strains was affected by removing IL10." (PMID 31527895, 2019). "NK cells have been well-recognized as potent pro-inflammatory cells due to their capability of secreting cytokines such as IFNγ and TNFα that limit microbial growth during the initial stages of infections." (PMID 31803193, 2019). "Lung airway CD8TRM cells provide protection against respiratory virus infection through IFNγ and help to recruit circulating memory CD8+ T cells to the site of infection in an IFNγ-dependent way." (PMID 31525249, 2019). "Rituximab and cyclophosphamide have been shown to improve infection by restoring the function of IFNγ in these patients." (PMID 31892200, 2019). "Patterned bars indicate conditions where the different cell types were treated with IFNγ prior to and throughout infection." (PMID 31204998, 2019).
infection (continued). "Examination of the response following lethal FT intranasal infection (LVS strain, 105 cfu, 100 LD50) established that three days following LVS infection there were more than 300 IFNγ spots per 106 splenocytes." (PMID 31443439, 2019). "We observed that huNSG mice that were infected with 105 infectious EBV particles also had significantly higher serum levels of IFNγ, TNFα, IL-10, and IL-2 compared to infection with 103 infectious EBV particles or PBS treated huNSG animals." (PMID 31145756, 2019). "HeLa cells were stimulated with 100 IU/mL IFNγ, infected with type I (RH) Toxoplasma gondii (Tg) and analyzed 6 hr post-infection." (PMID 30744806, 2019). "Re-infection of mice that had received IL-12 during their prior infection revealed that they had become resistant to the challenge, with the recall of anti-gonococcal antibody responses as well as IFNγ." (PMID 31681305, 2019). "Some of these genes are involved in the development of Natural Killer (NK) and adaptive T cell responses, leading to the production of Interferon gamma (IFN-γ) and resistance to infection." (PMID 30405608, 2018). "NK cells and T cells are abundant sources of IFNγ in response to infection 12 which can be recruited in response to virus‐infected mast cell products or IFN." (PMID 29235261, 2018). "Mice deficient in NO-synthesis by iNOS, especially in the context of infection, were shown to exhibit an enhanced Th1 response with higher IFNγ and less IL4 secretion." (PMID 30030528, 2018). "There is as yet insufficient evidence of the reliability of repeated interferon gamma release assays as an indicator of interval infection in these settings." (PMID 29801449, 2018). "In this study, we found a trend in increased bacterial burden in IFNγ neutralization in WT mice during super-infection." (PMID 30337919, 2018). "IFNγ upregulates IL-17, which is generated by Th-17 cells and among other actions recruits neutrophils to the site of infection, mediates macrophage accumulation, and feeds back to induce Th-1 cells to secrete more IFNγ." (PMID 29770360, 2018). "In humans, however, the adaptive response to Mtb (measured by a positive reaction to a tuberculin skin test (TST) or interferon gamma release assay) is characteristically delayed compared with other infections." (PMID 29520269, 2018). "Detailed analysis of both T. brucei and T. congolense infections has indeed shown that early IFNγ production is crucial for the control of the onset of infection." (PMID 30333827, 2018). "The most striking difference was the reduction of serum IFNγ and IL-12 in Ddx3xfl/y Vav-iCre mice at 24 hours after infection." (PMID 30475900, 2018). "Analysis of the relative contribution of CD8+ vs. CD4+ T cells to express IFNγ following v2.2-1 infection surprisingly revealed that CD4+ T cell express higher levels of IFNγ mRNA at the population levels than CD8+ T cells." (PMID 30619363, 2018). "In the current report, we establish a novel role for IFNγ in the development and resolution of protective CNS innate immune responses, after infection with HSV, a neurotropic 〈-herpesvirus." (PMID 29352287, 2018). "Data from this and earlier time points indicate that C. difficile-induced IFNγ expression is mostly MR1-dependent, suggesting that the cell contact with antigen-presenting cells is essential for IFNγ responses in the acute phase of infection." (PMID 30410474, 2018). "High levels of IFNγ are observed in early stages of infection, including latent stages, whereas a decline of IFNγ is predictive of progression to severe pathology, faecal shedding and disease." (PMID 29514687, 2018). "In A. phagocytophilum murine infection models, hepatic injury occurs with production of IFNγ thought to be derived from NK, NKT cells, and CD8 T lymphocytes." (PMID 29686681, 2018).
infection (continued). "In vitro infection of macrophages with BCG (Pasteur) alone showed minimal induction of Nos2, however in the presence of IFNγ infection with BCG caused a robust induction of Nos2 and accumulation of nitrite, indicating robust iNOS NO-producing activity." (PMID 30573728, 2018). "In contrast, mnd2tg mice exhibited heightened serum IL-18 levels 40 hours post-infection compared to littermate controls, concomitant with larger increases in the frequency of IFNγ-producing splenic NK cells." (PMID 29855523, 2018). "Yet, we have previously shown that Mtb-infection status is related to a decrease in IFNG production in TB as compared to HD, probably due to different evasion strategies of the mycobacteria." (PMID 29361774, 2018). "We observed that in this infection model, IFNγ produced in both the cKO and control mice by CD4+ T cells, CD8+ T cells and NKT cells were not altered." (PMID 30258450, 2018). "Despite possessing such mechanisms to evade the host IFNγ response, disseminated infections by many of these pathogens are prevented by the protective effects of IFNγ." (PMID 29855501, 2018). "In a murine animal model with Taenia crassiceps cysticercus, cellular immune response occurs in the early stage of infection characterized by the increase of interferon gamma (IFN-γ) and interleukin (IL)-2 levels." (PMID 30587902, 2018). "CD44-negative cells were reduced in their transcriptional response to interferon gamma (IFN-γ), viral DNA or infection with L. monocytogenes." (PMID 30540779, 2018). "C57BL/6 mice that were either mock-infected or infected with PyV, mCMV, and HV68 were sacrificed 40 days post-infection and splenocytes were co-incubated for 5 h with media alone, allogeneic (Balb/c) splenocytes, or viral peptides to assess IFNg production." (PMID 29963060, 2018). "IFNγ promotes M1-type macrophage polarization, cytokine production and synthesis of microbicidal mediators such as NO during infection with Mtb Erdman." (PMID 30374347, 2018). "Others have used interferon gamma (IFN-γ) knockout (KO) mice to model chronic infection, but the results from different research groups are variable, ranging from lethal infection in some cases to self-limited infection in others." (PMID 29339392, 2018). "Mice genetically deficient on IFNG or STAT1 display drastically augmented T. cruzi parasitism and 100% mortality 13 days after infection." (PMID 30559742, 2018). "We determine that infected murine microglia produce several pro-inflammatory cytokines as the result of direct infection, including IFNγ, IL-1α, IL-1β, IL-6, and IL-12." (PMID 30400156, 2018). "As for infection with T. evansi, the information on the role of IFNγ is limited, but data has shown that in addition to anti-trypanosome antibodies, this cytokine is required for parasitaemia control." (PMID 30333827, 2018). "Our analysis indicates that direct TC-83 infection of microglia results in production of numerous pro-inflammatory cytokines, including IFNγ, IL-1α, IL-1β, and IL12p70." (PMID 30400156, 2018). "BMDM were infected with BCG-GFP27 and the ROS production was assessed in infected BCG-GFP+ vs uninfected BCG-GFP− cells 2 h after initial infection with BCG-GFP/IFNγ." (PMID 30573728, 2018). "In contrast, pSTAT1 was observed to be nuclear if cells were pre-exposed to IFNγ for 24 hours prior to infection and maintained in IFNγ during infection." (PMID 29855501, 2018). "The Th1 responses and regulation of the recruitment of Th1 immune cells to the site of infection are characterized by expression of key cytokines and chemokine such as TNFα, IL-12, IFNγ, IL-6, IL-10 and MCP-1 among others." (PMID 30413750, 2018). "Taken together, NK and T cells were the major IFNγ-expressing cell types in the lungs during the peak of anti-MCMV immune response in an immunocompetent host leading to control of infection." (PMID 30153311, 2018).
infection (continued). "OT-II cells expressing both IFNγ and IL-2 significantly increased in LdWT (p = 0.0064) and LdCen−/− (p = 0.0489) infections upon blocking with α-CD200 antibodies." (PMID 29915577, 2018). "When C57BL/6 mice are infected with T. brucei the initial parasitaemic wave coincides with the expression of high levels of IFNγ by the host in an attempt to control the infection." (PMID 30467504, 2018). "Since we observed an impact of IL-27 on the number of antiviral CD4 T cells present upon infection, we also normalized numbers of IFNγ producing CD4 T cells to the number of polyclonal CD11a+CD49d+ antiviral CD4 T cells detected." (PMID 30044874, 2018). "Following infection with herpes simplex virus or contact sensitization to induce local inflammation, IFNγ producing CD4 T cells increased in the skin and clustered around hair follicles in association with CCL5 producing CD11b and CD8 T cells." (PMID 30386342, 2018). "The differential expression of IDO1 in bystander and infected cells after IFNγ exposure was recapitulated using infections at increasing IFU/mL, which resulted in the infections of 2%, 26% and >95% in A2EN cells." (PMID 29855501, 2018). "As for infections by most intracellular bacteria, IFNγ is an essential component of the innate immune response to B. pseudomallei and its absence results in severely decrease resistance to the infection." (PMID 29791511, 2018). "Very short-lived IFNγ levels were produced in antigen-specific stimulation analyses at the end of the first and during the second week following infection with N. caninum and prior to mounting a specific IgG response." (PMID 29739449, 2018). "Based on the data presented in this manuscript we envisage the following model how T cells contribute to the local control of MCMV in lung NIFs: T cells are primed in lymphoid organs and within NIFs to secrete IFNγ directly at the site of infection." (PMID 30153311, 2018). "The classical pathway gives rise to the M1 macrophages during an immune response to infection and is mediated by the Th1 cytokine interferon gamma (IFN-γ) and the toll-like receptor agonists, such as lipopolysaccharide (LPS)." (PMID 29495393, 2018). "Taking these results together, we concluded that Cm lung infection induces IFNγ secretion from Vγ4+ T cells at very early stage and Vγ1+ T cells at midstage of infection." (PMID 29670466, 2018). "Previous work from our group on acute melioidosis donors focused on the observation that patients who survived acute infection showed a T-cell IFNγ response to AhpC significantly greater than those who died." (PMID 29616023, 2018). "Large amounts of IFNγ and IL-17 existed at the early stage of infection participate in host immune response against Chlamydia infection." (PMID 29670466, 2018). "IFNγ+ CD4 T cells were also increasingly present in the BM over the course of infection; however, the frequency and numbers of these cells dropped at d35p.i., as observed in the spleen." (PMID 29472618, 2018). "The mitochondrial phosphorylation capacity was decreased by IFNγ and TNFα in combination, both when accompanied by infection (-48%, p<0.001) and under un-infected conditions (-36%, p<0.01)." (PMID 30252907, 2018). "Infection with T. gondii elicits a strong Th1-polarized immune response characterized by production of IFNγ, IL-12, and parasite specific IgG2a antibodies." (PMID 30467504, 2018). "In A. phagocytophilum murine infection models, inflammatory hepatic histopathologic injury is abrogated in Ifng−/− and enhanced in Il10−/− animals, confirming an important role for IFNγ in driving tissue injury." (PMID 29686681, 2018). "A multiplicity of infection (MOI) of five was used after induction with 100 U/mL murine recombinant IFNγ (R&D Systems) for 16 h." (PMID 29510761, 2018). "After Cm infection, the secretion of IFNγ was gradually increased and reached the peak at day 7 p.i. which had significant difference with uninfected group then declined to the basic level at day 14 p.i.." (PMID 29670466, 2018).